IL6 (interleukin 6)
Diseases named in the same sentence as IL6 in open-access papers (continued):
Sharing a sentence is not in itself a finding about the gene and the disease.
Obesity (continued). "It is well-established that both HFDs and obesity incite a chronic, low-grade inflammatory state due to upregulated NFkB and subsequent secretion of inflammatory cytokines such as IL-1, IL-6, and TNF." (PMID 31196172, 2019). "Obesity is an inflammatory disease and ENOblock treatment reduced expression of the inflammatory markers Il-6 and Tnf-α." (PMID 30679508, 2019). "Thereby, IL-6 contributes to the adaptation of β-cell function to the increased insulin demand in physiology and obesity." (PMID 30989320, 2019). "The adipokines such as leptin, adiponectin, IL-6, and TNF-α show prominent effects on adipocyte metabolism and utilization of insulin and, therefore, exhibit a strong association with obesity and related metabolic disease." (PMID 31597283, 2019). "TNF-α and IL-6 are cytokines that are synthesized in ATM and increased with lipid accumulation; thus, these cytokines are indicators of obesity-associated inflammation." (PMID 30889894, 2019). "IL-6 is an inflammatory biomarker that is positively correlated with obesity, glucose intolerance, and insulin resistance." (PMID 31093012, 2019). "We sought to investigate the possible role of the pro-inflammatory state on such alteration, considering the effect of the expression of markers, such as leptin and IL6, which are notably high in obesity." (PMID 31664059, 2019). "The relationship between obesity, periodontal status and serum IL-6 remains controversial due to the role of TNF-α." (PMID 31365708, 2019). "Clinically, several inflammatory mediators including IL-6 are proposed to increase the risk of DVT in various types of pathological conditions such as surgery, obesity, cystic fibrosis, sepsis, systemic infection, cancer, inflammatory bowel disease, and lupus." (PMID 32117207, 2019). "IL-6 circulating levels have been systematically reported to be augmented in obesity, being visceral fat secretion an important source of IL-6 thus linking the enlarged visceral fat with the existence of systemic inflammation in obese patients." (PMID 31178685, 2019). "Obesity is associated with inflammation and inflammatory cytokines including TNF-α, IL-6 and resistin promote phosphorylation of insulin receptor substrates 1 (IRS-1) at serine sites that negatively regulates normal insulin signaling." (PMID 31226166, 2019). "Two recent studies further biologically validate IL-6 at the level of adipose tissue as treatment for obesity and at the level of the gut for the control of gastric emptying." (PMID 31686269, 2019). "Taken together, our results suggest that obesity promotes CNS inflammation in EAE through IL-6 and CCL-2 mediated the inflammatory cells infiltration." (PMID 31507583, 2019). "We have shown that IL-6 appears to be protective against the renal changes that this imbalance of crosstalk in obesity creates." (PMID 30871285, 2019). "Leptin, which is augmented in obesity, also up-regulates pro-inflammatory cytokines, such as TNF-α and IL-6, which are associated with insulin resistance and the development of type II diabetes." (PMID 31357412, 2019). "We considered the blood levels of IL-6 and hs-CRP as inflammatory markers implicated in obesity and metabolic disorders." (PMID 31440209, 2019). "Due to obesity, the levels of adipocytes, cytokines (interleukin-1 (IL-1) and interleukin-6 (IL-6)), and tumor necrosis factor alpha (TNFα)) increases in the body." (PMID 31470636, 2019). "In the EPI depot, melatonin reversed the increase of leptin, Il-6, Mcp-1 and Tnf-α triggered by obesity." (PMID 31489938, 2019). "Obesity and the metabolic syndrome are accompanied by a ‘low grade’ chronic inflammation, indicated by a well-characterized positive association between obesity indices and inflammatory markers, such as C reactive protein (CRP) and IL-6." (PMID 30639417, 2019).
Obesity (continued). "The pro-inflammatory signaling molecules generated by adipocytes in obesity like IL-6 and leptin reach high systemic levels and trigger insulin resistance, developing type 2 diabetes and other complications." (PMID 30605486, 2019). "Obesity is closely related to the pathogenesis of type 2 diabetes, as long-term obesity will lead to IL-6 and IL-17-mediated chronic inflammation." (PMID 31849847, 2019). "Chronic JAK-STAT3 signaling induced by IL-6 leads to the increased expression of suppressor of cytokine signaling-3 that not only negatively regulates IL-6 signaling but also hinders insulin action, eventually resulting in obesity and IR." (PMID 32063863, 2019). "Especially IL-6 is thought to play a significant role in early OA and also seems to increase with a higher grade of obesity (BMI > 30), which applies only partly to our patient cohort." (PMID 31590365, 2019). "IL-6 is released under inflammation and is involved in the insulin resistance of obesity or diabetes." (PMID 30555329, 2018). "Here we investigate the role of obesity-induced IL-6 during development and progression of CAC in mice." (PMID 29695802, 2018). "TNF-α and IL-6 are pro-inflammatory cytokines synthesized when the lipid content increases in WAT, contributing to the pathogenesis of obesity-linked complications." (PMID 30360535, 2018). "Here, we review the current state of knowledge on how obesity affects inflammatory TNFα and IL-6 signaling in hepatocellular carcinoma and colorectal cancers." (PMID 30591653, 2018). "Pregravid obesity is characterized by insulin and leptin resistance, high levels of circulating inflammatory markers IL-6 and CRP, in addition to chemokine IL-8 (p < 0.01)." (PMID 30131724, 2018). "Some inflammatory cytokines such as interleukin-6 (IL-6) and Tumor necrosis factor-α (TNF-α) have also been implicated in obesity-related CKD." (PMID 30359237, 2018). "Obesity is also strongly linked to IR, which may be the result of hepatic IR caused by stimulation of the pro-inflammatory M1 macrophages in adipose tissues, which release interleukin-6, tumor necrosis factor-alpha, and free radicals that produce oxidative stress." (PMID 29415050, 2018). "One possible explanation is that, in RA, persistently heightened systemic IL-6 contributes to sarcopenic obesity by impairing the normal muscle adaptive responses to exercise training." (PMID 30587230, 2018). "IL-6 signaling in NK cells was shown to drive their reprogramming into cells with myeloid gene expression and thereby impair insulin action in obesity." (PMID 30591653, 2018). "Obesity increases the production and release of pro-inflammatory adipokines, including leptin and IL-6." (PMID 29949600, 2018). "Studies of obesity and prostate cancer revealed that the periprostatic adipose tissue secretes high levels of interleukin-6 (IL6), compared to subcutaneous adipose tissue, which modulates cancer aggressiveness." (PMID 29887999, 2018). "Percent body fat, plasma inflammatory markers associated with obesity (interferon (IFN)-γ, interleukin (IL)-10, IL-12 p70, IL-1β, IL-6 and KC/GRO), plasma Cur metabolites and liver telomere length were measured." (PMID 29445415, 2018). "Obesity-induced interleukin-6 (IL-6) shifts macrophage polarisation towards tumour-promoting macrophages that produce the chemokine CC-chemokine-ligand-20 (CCL-20) in the CAC microenvironment." (PMID 29695802, 2018). "Omentum removal reversed immediately the increased plasma levels of CRP and IL-6 and gradually food intake, weight gain, and features of MS in diet-induced-obesity." (PMID 29367725, 2018). "Recently, it was reported that selective blocking of IL-6 signaling in T cells improves glucose homeostasis and ameliorates liver steatosis in high-fat diet-fed mice, but only early in the development of obesity." (PMID 29868016, 2018).
Obesity (continued). "Taken together, these studies demonstrate that TNFα and IL-6, either induced by obesity or the colonic tumor microenvironment, exert their function mainly on infiltrating immune cells and, to a lesser extent, on intestinal cells to promote CRC." (PMID 30591653, 2018). "Overall, our experiments assign obesity-induced IL-6 an unappreciated role in the CAC TME by regulating macrophage polarisation and lymphocyte recruitment." (PMID 29695802, 2018). "IL-6-deficient mice exhibit mature-onset obesity, with disrupted carbohydrate and lipid metabolism, which are partially reserved by intracerebroventricular (ICV) injection of rat IL-6." (PMID 30134607, 2018). "Increased intra-abdominal pressure, gastroesophageal reflux and altered levels of adipokines and cytokines (leptin, TNFα, IL-6 and IL-17) from obesity have been proposed as potential GCA promoting factors and reviewed in depth." (PMID 30567335, 2018). "Some authors demonstrated that obesity is associated with an inflammatory process, characterized by increased circulating levels of inflammatory cytokines such as TNF-α, IL-6, and C-reactive protein (CRP)." (PMID 29780825, 2018). "The anthropometric measures, obesity-related biochemical results, and levels of tumor necrosis factor-α, interleukin-6, caspase-cleaved cytokeratin fragment of cytokeratin 18 (M30), and adiponectin were also checked." (PMID 30671426, 2018). "The proinflammatory cytokine interleukin-6 (IL-6), frequently elevated in obesity, has been shown to induce expression of hepcidin, a negative regulator of intestinal iron absorption, macrophage iron efflux and mobilisation of hepatic iron stores." (PMID 30061547, 2018). "We and others have shown that IL-6Rα-deficient macrophages stay in the proinflammatory M1 state, while obesity-induced IL-6 shifts macrophage polarization towards the tumor-promoting M2 state." (PMID 30591653, 2018). "Among them, MCP-1, TNFα, interleukin IL-1 and IL-6 have been reported to promote obesity related-insulin resistance." (PMID 29507613, 2018). "In summary, high concentrations of free fatty acids play an important role in the activation of TLR4/NF-κB/IL-6 inflammatory signaling pathways by promoting the expression of KLF7 in obesity." (PMID 30598636, 2018). "Here the authors show in mouse models that obesity-induced interleukin-6 alters macrophage function to enhance CCL-20/CCR-6-mediated recruitment of B cells and γδ T cells, thereby promoting gut inflammation and CAC progression." (PMID 29695802, 2018). "Our group also noticed that cardiac FAT/CD36 mRNA levels increase during HFD-induced obesity in both WT and IL-6−/− mice." (PMID 30134607, 2018). "Male and female C57BL6 mice fed HFSD containing 60% fat along with drinking water containing 42 g/L sugar (55% sucrose/45% fructose) for 12 weeks exhibited significant obesity, hyperglycemia, and elevated plasma IL-6 levels." (PMID 30348225, 2018). "Obesity was identified as a state of chronic, low-grade inflammation due to systemic elevated expression levels of tumor necrosis factor alpha (TNFα) and IL-6." (PMID 30224299, 2018). "MCP-1, in concert with other pro-inflammatory cytokines such as TNF-α or IL-6 overexpressed by adipocytes in obesity and MetS, leads to insulin sensitivity." (PMID 29507613, 2018). "Obesity normalizes systemic and skeletal muscle levels of IL‐6 between p50−/− and WT, but elevated TNFα (skeletal muscle and adipose tissue) and IL‐6 (liver and adipose tissue) expression is maintained." (PMID 30251338, 2018). "In our studies, IL6 upregulation, seen after BP3 treatment, matches with improved insulin sensitivity, obesity and steatosis in IL6 transgenic mice, likely by suppressing gluconeogenic and lipogenic enzymatic cascade via hepatic STAT3 phosphorylation." (PMID 30374109, 2018).
Obesity (continued). "Certain cytokines in the clusters have already been established as distinguishing among high inflammatory, metabolically abnormal and low inflammatory, metabolically healthy subtypes of obesity, such as IL-6." (PMID 29738558, 2018). "It was proposed by Frasca and Blomberg that increased hypoxia and CCL-2 expression, along with increased adipocyte-derived TNF-α, IFN-γ, IL-6, and IL-21, prompted an obesity-driven accumulation of pro-inflammatory B-cells, which is exacerbated with ageing." (PMID 29479350, 2018). "The association between obesity and chronic inflammation is suggested by several observations, such as the production of TNF-α and IL-6 by adipocytes in obese mice and humans as well as the presence of immune cells (i.e., macrophages) in adipose tissue." (PMID 30201891, 2018). "But adipocytes have the capability to stimulate ASMCs to release eotaxin and IL-6, which are pro-inflammatory in nature, thereby contributing to the chronic inflammatory state, archetypal for both asthma and obesity." (PMID 29486749, 2018). "Obesity promotes macrophage recruitment and the secretion of numerous inflammation cytokines as TNFβ, IL-1, IL-6, and IL-18." (PMID 30390093, 2018). "Collectively, our study assigns obesity-induced IL-6 as a modulator of the TME in CAC via macrophage polarisation and successive lymphocyte recruitment via the CCL-20/CCR-6 axis." (PMID 29695802, 2018). "In turn, the proinflammatory cytokines including IL-6 and TNF-α can be promoted by resistin, thus decreasing obesity-associated inflammation." (PMID 30050954, 2018). "These authors went further and showed that chronic ICV injection of rat recombinant IL-6 reduces relative weight of mesenteric and retroperitoneal fat pads, thereby suggesting the anti-obesity role of IL-6." (PMID 30134607, 2018). "Sleep loss, for instance, is known to induce proinflammatory markers CRP, Interleukin-6 (IL-6) and TNF that are associated with depression and obesity." (PMID 30524737, 2018). "Leptin and IL-6 activate similar downstream signaling pathways and both are increased in circulation upon obesity." (PMID 30224299, 2018). "Adipose tissue contains multiple types of cells, including adipocytes, macrophages and immune active cells, all metabolically active in producing IL-6, especially in the context of obesity." (PMID 29951282, 2018). "Circulating IL-6 is elevated due to obesity, resulting in hepatic insulin resistance, which implies that IL-6 has unfavorable effects on glucose metabolism." (PMID 29694426, 2018). "As a key immune mediator of the low-grade chronic inflammation in obesity, elevated serum IL6 and CRP levels are characteristically found in obese patients and considered as risk factors for T2DM development." (PMID 30158466, 2018). "On the other hand, it is well known that IL-6 is an inflammatory cytokine and serum IL-6 concentrations are generally increased in subjects showing obesity, diabetes and NAFLD." (PMID 30374329, 2018). "To gain further insights into the molecular mechanisms that promote CAC via obesity-induced IL-6, we compared global gene expression in obese control vs IL-6Rα-deficient tumour samples by microarray." (PMID 29695802, 2018). "Omentum drives obesity progression through leptin resistance mediated by C-reactive protein, Interleucin (IL)-6 and high lipolysis activity." (PMID 29367725, 2018). "Obesity-related elevations in IL-6 appear to help fuel the process of low-grade inflammation that accompanies obesity in a feedback response designed to offset energy excess." (PMID 30093853, 2018). "This mouse model was also resistant to diet induced obesity and inflammation, as measured by serum levels of IL6, TNFA and IL1." (PMID 30158466, 2018). "A study have reported that ethanol extract of ginger ameliorated obesity and inflammation through inhibition of adipose tissue accumulation and mRNA expression of pro-inflammatory cytokines such as IL-6 and TNF-α in WAT of mice fed high-fat diet." (PMID 30360535, 2018).
Obesity (continued). "Lastly, obesity networks (e.g., transcripts including Retn, Lpl, Lep, Esr1, Lipc, Hsd11b1, Gpt, Lipe, Vldlr, and Il6, among others, fold change −1.042, P < 0.05) were also decreased by 4% (1.04-fold)." (PMID 28446880, 2017). "Insulin resistance and obesity are characterized by a low-grade but chronic inflammatory state, with elevated circulating levels of CRP, TNF-α, IL-6 and leptin and reduced ACDC concentrations associated with increased cardiometabolic risk." (PMID 29020958, 2017). "IL-6 is also known to be associated with metabolic disorders, and has been found to be up-regulated in NAFLD and obesity-related HCC." (PMID 28273155, 2017). "Overexpression of IL-6 therefore induces multiple inflammatory symptoms, chronic fatigue, insomnia, and obesity." (PMID 29292401, 2017). "A strong association has been reported among the extent of infiltrating adipose tissue macrophages, other pro-inflammatory immune cells and several pro-inflammatory mediators (TNF-α, IL-1β, and IL-6), which are enhanced in obesity." (PMID 29064461, 2017). "In previous studies, expression level of IL6 in adipose tissue and circulating concentrations of IL6 positively correlates with obesity and insulin resistance." (PMID 28706200, 2017). "This study evaluated the importance of TNF-α, IL-6, and IL-10 levels and their association with gene polymorphisms in T2DM disease and the obesity." (PMID 28225860, 2017). "As inflammation is a common feature of obesity we measured plasma levels of two cytokines associated with the progression of CVD, IL-6, and TNF-α, in our 4 groups of mice." (PMID 28184201, 2017). "In summary, there are functional IL‐6Rα on tanycytes at the bottom of the 3V, in agreement with the possibility that ventricular administration of IL‐6 decreases obesity in mice via an effect on this cell type." (PMID 29024103, 2017). "In fact, the development of insulin resistance and type II diabetes, even independent from obesity, can be predicted by an increase in inflammatory markers like interleukin 6 (IL-6) and C-reactive protein (CRP)." (PMID 28704429, 2017). "Apart from the impact on adipose tissue expansion during obesity, IL-6, as the most important regulator of numerous functions in central nervous system, is widely expressed in hypothalamic region that regulates appetite and energy intake." (PMID 29163240, 2017). "Regarding obesity, it is generally known that proinflammatory cytokines such as IL-6, TNF-ɑ and innate immune mediator increase in the adipose tissue." (PMID 29021828, 2017). "Systemic level of IL-6 strongly correlates with obesity and insulin resistance and serum concentrations of IL-6, sIL-6R, and gp130 are elevated in patients with metabolic syndrome (MetS) and related cardiovascular disorders." (PMID 29163240, 2017). "In fact, fatty acid binding protein 4 (FABP4)/IL-6/STAT3/DNA methyltransferase 1 (DNMT1) have been shown to link obesity to the growth of AML cells." (PMID 29269861, 2017). "One of the main effects of IL-6 is the induction of hepatic CRP and FIB production, playing a key role in the inflammatory processes associated with obesity." (PMID 28061787, 2017). "Obesity makes an increase in severity of AP through a mechanism of IL6, IL8, and other inflammatory mediators." (PMID 28331492, 2017). "In the present study, calpain inhibition reduced obesity-induced pro-inflammatory gene expression including TNFα, IL-6, and IL-1β in adipose tissue." (PMID 29089532, 2017). "Chronically high, even if moderately, IL-6, characterizing chronic inflammatory conditions (e.g., obesity, sedentariness) stimulating the hepatic synthesis of this cytokine, cause pro-inflammatory, and potentially deleterious effect." (PMID 28512432, 2017). "We evaluated the associations of diabetes, combined with the polymorphisms in the genes of fat mass and obesity-associated gene (FTO), interleukin 6 (IL-6), and heat shock protein 60 (HSPD1), with breast cancer risk and survival in a Chinese Han population." (PMID 28591216, 2017).